GADD45B (growth arrest and DNA damage inducible beta)
Diseases named in the same sentence as GADD45B in open-access papers (continued):
Sharing a sentence is not in itself a finding about the gene and the disease.
pancreatic neuroendocrine tumor (1 paper, 2012). Pancreatic endocrine tumor, also known as pancreatic neuroendocrine tumor (PNET), describes a group of endocrine tumors originating in the pancreas that are usually indolent and benign, but may have the potential to be malignant. "The hierarchical clustering of 19 pancreatic neuroendocrine tumors (PNETs) revealed that GADD45B was one of the most highly up-regulated genes in the malignant group of PNETs." (PMID 23110778, 2012).
periodontitis (1 paper, 2017). An acute or chronic inflammatory process that affects the tissues that surround and support the teeth. "It would be interesting to further investigate the role of GADD45b in the development of periodontitis in elderly subjects." (PMID 29190775, 2017). "In contrast, the roles of GADD45B and BIRC3 have not been thoroughly investigated in the progression of periodontitis." (PMID 29190775, 2017).
psychostimulant addiction (1 paper, 2021). "Moreover, shRNA-induced Gadd45b knockdown decreases expression of genes involved in psychostimulant addiction, blocks induction of immediate early genes by DRD1 stimulation, and prevents DRD1-mediated changes in DNA methylation." (PMID 32927466, 2021).
retina degeneration (1 paper, 2025). "Among the downregulated genes were Edn2, a known marker of retina degeneration, Gadd45b, a stress response gene, and Igrm1, a gene that positively regulates macroautophagy." (PMID 40643481, 2025).
rhabdomyosarcoma (1 paper, 2015). A rare aggressive malignant mesenchymal neoplasm arising from skeletal muscle. "So far this study on Rhabdomyosarcoma has investigated 5 of them (p21CIP1, p15INK4B, CTGF, GADD45B and SGK)." (PMID 25806826, 2015).
Salmonella Infections (1 paper, 2018). Infections with bacteria of the genus SALMONELLA. "On the other hand, FOXO signaling (TNFSF10, PRKAB1, GADD45B, STK4, STAT3), Salmonella infection (ARPC2, ARPC5L, CCL3L3, CCL4) and lysosome (LAPTM4B, HGSNAT, CD164, ATP6V0A2) pathways were up-regulated, albeit weakly, in the HLA-DR- Teff subset." (PMID 30231065, 2018).
serous ovarian cancer (1 paper, 2010).
thymoma (1 paper, 2019). A neoplasm arising from the epithelial cells of the thymus. "Real-time PCR analysis confirmed that CCL25 was upregulated; and MYC, GADD45B, TNFRSF12 downregulated in thymoma with MG." (PMID 30787364, 2019).
ulcerative colitis (1 paper, 2019). An inflammatory bowel disease involving the mucosal surface of the large intestine and rectum. "They showed that a mouse model of chemically induced ulcerative colitis exhibited more severe disease symptoms and higher mortality when these animals also lacked Gadd45β." (PMID 31666502, 2019).
Waldenström’s macroglobulinemia (1 paper, 2014). "DTP3, in fact, could also distinguish between PCs from MM and Waldenström’s macroglobulinemia (WM) patients, in line with the GADD45B expression levels in these cells, whereas bortezomib could not." (PMID 25314077, 2014).
ZIKV infection (1 paper, 2018). "Selected genes blocking cell growth (DDIT3, GADD45B, and CDKN2B) were significantly upregulated by ZIKV infection." (PMID 30228241, 2018).
cancer (74 papers, 2005 to 2025). A tumor composed of atypical neoplastic, often pleomorphic cells that invade other tissues. "Phenethyl isothiocyanate (PEITC) is a component of cruciferous vegetables with proven anti‐cancer activity in many cancer models, and its benefit has also been associated with increased Gadd45β expression." (PMID 39653679, 2024). "Conversely, increased GADD45B expression levels were associated with shorter recurrence-free and overall survival in the most prevalent and aggressive human cancer types." (PMID 32425887, 2020). "This was probably caused by the altered regulation pattern of GADD45B-network in cancer environment." (PMID 31681565, 2019). "IPA at 4 h revealed that 7 genes [Btg2, Ccng2, Cdkn1a, Gadd45b, Gadd45g, Phlda3, and Mdm2] of 18 genes, which showed statistically significant increases, were associated with cancer, cell cycle, cell death and survival, and cellular growth and proliferation." (PMID 27482301, 2016). "Many of these upregulated genes, like Gadd45b and Wisp1, influence cell cycle/death and are associated with cancer." (PMID 21455306, 2011). "For example, we found that the different genotypes of SNP GADD45B E1122 are all associated with cancer risk." (PMID 16026601, 2005). "However, in other tumors, the authors also demonstrated that macrophage-specific Gadd45β loss blocks oncogenesis, indicating that Gadd45β governs the immunosuppressive activity of the TME across multiple cancer types." (PMID 38397187, 2024). "Our new finding through a cancer patient database analysis which suggests low survival rates associated with low GADD45β expression levels in the liver further prompted us to focus on Gadd45β." (PMID 37746289, 2023). "One gene involved in free radical scavenging, SOD3, was downregulated, whereas the genes associated with cell cycle or cancer, including GADD45B, ID1, KLF10, CSRNP1, and TM4SF1, were upregulated in F. nucleatum-infected GF(P22) cells when compared to F. nucleatum-infected GF(P4) cells." (PMID 29190775, 2017). "Reciprocal regulation of the putative tumor suppressor gene Tsc22d1, which leads to the suppression of Gadd45b and that of other cancer‐associated target genes (Iida, Anna, Gaskin, Walker & Devereux, 2007), may also account for the lower rate of tumor progression in RedTg livers." (PMID 29706024, 2018). "Gadd45β was selected since it has emerged as a promising therapeutic target involved in multiple disease pathways, including cancer and inflammation." (PMID 41251395, 2025). "NF-κB signaling can increase cancer cell-intrinsic expression of critical antiapoptotic mediators, including Bcl-xL, Bcl2, cFLIP, cIAP2 and Gadd45β by promoting tumor growth and protecting cancer cells from apoptosis-inducing chemotherapeutic agents." (PMID 36768145, 2023). "GADD45B had an impact on cancer differentiation, especially in patients with G2 and G3 stage tumors, where there were differences in the expression levels of GADD45B." (PMID 37608794, 2023). "Correlation of GADD45B expression with clinico-pathologic characteristics of PCa patients in Sun Yat-sen University Cancer Center (106 patients)." (PMID 34490266, 2021). "Our finding indicated that CuE in the explored cancer cells led to down‐regulation of the association of the cyclin B1/CDC2 complex and the up‐regulation of GADD45β." (PMID 30912292, 2019). "Future studies will determine the clinical safety and therapeutic efficacy of DTP3 in patients with MM and potentially other cancers in which NF-κB drives oncogenesis via GADD45β." (PMID 31080744, 2019). "DTP3 is a small peptide inhibitor of the GADD45β/MKK7 complex and is able to restore MKK7/JNK activation, thereby promoting selective cell death of GADD45β-overexpressing cancer cells." (PMID 29572137, 2018). "Our recent studies demonstrated that elevated GADD45β expression promotes cancer-cell survival in MM cells, and that disrupting the GADD45β/MKK7 complex spontaneously restores apoptosis by inducing sustained JNK activation." (PMID 29572137, 2018).
cancer (continued). "The widespread correlation between GADD45B expression and poor clinical outcome in human cancers underscore the general clinical significance of the NF-κB-dependent mechanisms mediated by GADD45β in oncogenesis." (PMID 29511335, 2018). "Constitutive GADD45β expression depends upon NF-κB activation and is largely restricted to certain types of cancer cells, such as malignant MM plasma cells." (PMID 29572137, 2018). "In conclusion, GADD45β induction by SAMe enhanced its inhibitory effects on cancer cell proliferation during I/H by increasing apoptosis." (PMID 27177086, 2016). "By exploiting the GADD45β/MKK7 complex it would be realistic to inhibit the cell survival axis of the NF-κB signalling complex in cancer cells to achieve clinical activity with a broad therapeutic window." (PMID 27441658, 2016). "GADD45β belongs to the growth arrest- and DNA damage-inducible protein family and is related to NF-kB, which is known to influence tumorigenesis, cancer cell survival, apoptosis, invasion, and metastasis." (PMID 21048853, 2010). "The representation of GADD45B in SKCM and its association with clinical characteristics were examined in this study using data on GADD45B gene expression from the TCGA (the cancer genome atlas) and GEO (gene expression omnibus) databases as well as the associated clinical data." (PMID 40350499, 2025). "Notably, MP7 was associated with stress meta program (MP5) in pan‐cancer studies, sharing 14 common genes, including ATF3, EGR1, FOSB, GADD45B and NR4A1." (PMID 40292733, 2025). "Doxorubicin, a widely used chemotherapeutic agent known to regulate DNA damage, cell-cycle arrest, and apoptosis, can perturb the expression of several cancer driver genes (GADD45B, UHRF1, CDC6, etc.)that are involved in cell-cycle regulation, from this high-throughput data analysis." (PMID 41431699, 2025). "After AHPN treatment, Gadd45β expression rapidly increased in many cancer cell lines." (PMID 39653679, 2024). "In human cancer, GADD45B has been reported either as tumor suppressor gene or as oncogene." (PMID 38297314, 2024). "Moreover, other genes upregulated in distinct but also specific stimuli like PPA1, GADD45B, C1D, TRPV2 and RPS14 were associated with DDR, cancer and apoptosis." (PMID 39623312, 2024). "Since Gadd45β has been considered to play an anti-tumor role in some cancers, our logical hypothesis was that this molecule is playing a key role in HCC tumorigenesis." (PMID 37746289, 2023). "The Cancer Genome Atlas, Gene Expression Omnibus datasets, and clinical samples were used to examine the correlation between growth arrest and DNA damage-inducible 45 beta (GADD45B) with clinical characteristics and prognosis." (PMID 34490266, 2021). "Although GADD45B might be up-regulated and responsible for carcinogenesis under DNA damage response in a few cases, many studies have presented that downregulation of GADD45B contributes to tumorigenesis and malignant development in human cancers." (PMID 31296259, 2019). "GADD45B inhibits cancer development in a variety of situations." (PMID 31681565, 2019). "Interestingly, GADD45β mediates these diverse oncogenic functions through distinct mechanisms, which suppress cancer-cell apoptosis by inhibiting MKK7/JNK activation and curb inflammation by attenuating macrophage-associated p38 signalling." (PMID 29511335, 2018). "Interestingly, reports have shown the existence of cross talk between the TNFα‐NFkB signaling pathway and the coactivator Gadd45β, and strong staining of GADD45β has also been detected in multiple human cancer tissues." (PMID 29706024, 2018). "BIRC5 and GADD45B are involved in apoptosis, one of the most important hallmarks of cancer." (PMID 29304754, 2018).
cancer (continued). "GADD45β is related to NF-kB, which is known to influence tumorigenesis, cancer cell survival, apoptosis, invasion, and metastasis and the GADD45 family are essential mediators of cell survival in cancer cells with implications for cancer chemotherapy and novel drug discovery." (PMID 30029519, 2018). "Furthermore, it was found that methylation was involved in the downregulation of Gadd45β, and induction of Gadd45β by treatment of cells with DNA methyltransferase inhibitor (5-azacytidine) also increased the sensitivity of cancer cells to chemotherapy." (PMID 29225771, 2017). "5-azacytidine (5-AZA) is the DNA methyltransferase (DNMT) inhibitor, thus we hypothesized that induction of Gadd45β by pretreatment of 5-azacytidine would increase sensitivity of cancer cells to chemotherapy." (PMID 29225771, 2017). "Thus, FNDC5 has cooperative effects with GADD45B on prognosis of cancer patients." (PMID 37746289, 2023). "Additionally, GADD45B is either an oncogene or tumor suppressor gene in different cancers." (PMID 34490266, 2021). "Therefore, innate immunotherapies targeting GADD45β could plausibly overcome immunotherapy resistance, increasing response rates in otherwise refractory cancer patients." (PMID 29511335, 2018). "Growth arrest and DNA damage-inducible 45 alpha and beta (GADD45A, GADD45B) genes, which are involved in the MAPK pathway and overexpressed in our study, have important roles especially in cancer mechanism." (PMID 39838121, 2025). "The RCC score includes a panel of 12 genes, with 7 cancer-related genes (stromal genes: INHBA, BGN, and cell cycle genes: MKI67, MYC, MYBL2, GADD45B) and 5 reference genes, and is used to predict CRC recurrence." (PMID 40664638, 2025). "Consequently, GADD45B expression could plausibly be related to augmented sensitivity of neoplastic cells toward clinically administered therapies, thereby contributing to extended cancer patient survival duration." (PMID 40350499, 2025). "Therefore, targeting Gadd45β, in combination with conventional immunotherapies, could be a potential new therapeutic approach to counterstain Gadd45β-mediated tumorigenesis in human cancers." (PMID 38397187, 2024). "COL27A1, PRUNE2, MAEA, TBC1D3, GADD45B, ANXA8 and TSPY1 have been confirmed to play a pro‐resistant role in various cancers, which reflects the reliability of the hGeCKO library screening to some extent." (PMID 39550701, 2024). "Other proteins, such as GADD45B and HSPB1, are known to be involved in stress response and cellular homeostasis, which are critical in tumorigenesis and cancer progression." (PMID 39763976, 2024). "All the other genes (ATF3, EMP1, GADD45B, SOCS3, and ZFP36), distinct from EGR3, have been independently demonstrated to function as migration inhibitors in cancer cells." (PMID 38543002, 2024). "To gain insight into all correlations and clinical valorization of GADD45B/LSD1 in HCC, we investigated the mRNA levels of GADD45B and KDM1A genes in HCC cells by using Cancer Cell Line Encyclopedia dataset." (PMID 37250145, 2023). "The quantitative PCR analysis displayed the fold changes of three related genes (GADD45B, SENS2 and BBC3) for MD12a and compound 3, which were applied to HepG2 and MCF-7 cancer cells." (PMID 34830055, 2021). "siRNAs specific for MAP2K3 were designed and transfected into SFE-treated cancer cells to determine the relationship between SFE and GADD45B." (PMID 32873775, 2020). "Other genes, including GATA2, GADD45B, and MIR126, are differentially methylated in WD liver and blood, also play a role in epigenetic mechanisms in cancer." (PMID 30709419, 2019). "Accordingly, the GADD45β/MKK7 complex is an essential, cancer cell-restricted survival module downstream of the NF-κB pathway." (PMID 29572137, 2018). "Due to these properties of its therapeutic target, GADD45β/MKK7, DTP3 displays potent and cancer-selective activity against MM cells, both in vitro and in vivo, and is not toxic to normal tissues." (PMID 29572137, 2018).
cancer (continued). "GADD45β physically interacts with the JNK kinase, MKK7, inhibiting its activity to enable the survival of cancer cells." (PMID 29572137, 2018). "Rather than targeting NF-κB, we targeted the downstream module, GADD45β/MKK7, within a pathogenically critical and cancer-restricted axis of the NF-κB pathway." (PMID 25314077, 2014). "Cancer cells would activate the NF-κB pathway to up-regulate the expression of anti-apoptotic genes, such as c-IAP-1, c-IAP-2, Bcl-Xl, Gadd45β, and Survivin, to avoid apoptosis." (PMID 23718853, 2013). "In cancer cells, the treatment with etoposide or bleomycin induces the increased expression of the DDR factor growth arrest and DNA damage-inducible beta (Gadd45b), which is reduced in Nono-deficient cells." (PMID 40352720, 2025). "Gadd45β expression is significantly reduced in NAFLD‐related HCC, which may be related to its mediated anti‐cancer effect." (PMID 39653679, 2024). "Moreover, Gadd45β can inhibit the stemness of HCC cells and enhance apoptosis induced by chemotherapy for cancer." (PMID 39653679, 2024). "Taken together, these results suggested that shikonin might affect the expression of GADD45B and PPP3CC through the JNK/P38/MAPK pathway, therefore exerting an inhibitory effect on the proliferation and migration of cancer cells." (PMID 38167059, 2024). "From the quantitative PCR analysis, it was seen that (1E,4E)-1,7-bis(3,4,5-trimethoxyphenyl)hepta-1,4-dien-3-one (compound MD12a) effectively induced the up-regulated expression of GADD45B, leading to the suppression of MCF-7 cancer cell formation and cell death." (PMID 34830055, 2021). "Gadd45β is a protein that plays a pivotal role in negative growth control, including growth arrest and apoptotic cell death related to cancer." (PMID 32570293, 2020). "The persister gene panel (LYNX1, SYNPO, GADD45B, and PDLIM1) was established and its role to elucidate radio-response and clinical outcome after radiotherapy was subsequently validated across several cancer types." (PMID 33330109, 2020). "Again, genes such as GADD45B (growth arrest and DNA-damage-inducible, beta), HDAC1 (histone deacetylase 1), and MCM3 (minichromosome maintenance complex component 3) were oppositely coordinated in the cancer nodule in contrast to the normal tissue." (PMID 33302383, 2020). "Recently, we identified the complex formed by NF-κB-regulated antiapoptotic factor, GADD45β, and the c-Jun N-terminal kinase (JNK)-activating kinase, MKK7, as an essential, cancer-selective survival module downstream of NF-κB and novel therapeutic target in MM [11,]." (PMID 31080744, 2019). "This notwithstanding, our findings suggest that targeting the NF-κB pathway through GADD45β would provide an effective means to counter oncogenesis by reversing TME-mediated immunosuppression and, concurrently, inducing cancer-cell apoptosis, thereby providing dual therapeutic benefit." (PMID 29511335, 2018). "Hence, D-tetrapeptide antagonists of the GADD45β/MKK7 complex show exceptionally high activity and cancer cell specificity in terms of apoptosis induction in MM cells, without displaying any apparent toxicity to normal cells." (PMID 25314077, 2014). "Collectively, together with the data in primary MM cells, these results underscore the potency, safety, and cancer cell specificity of the pharmacological approach targeting the GADD45β/MKK7 complex in MM and identify DTP3 as a therapeutic selectively inhibiting the NF-κB survival pathway in cancer." (PMID 25314077, 2014). "The CSC-like phenotype of cancer SP cells might not only be determined by ABCG2, but also by GADD45β." (PMID 21048853, 2010). "Overall, Gadd45β decreases in HCC and may serve as a target for cancer treatment." (PMID 39653679, 2024).